RNU6-473P (RNA, U6 small nuclear 473, pseudogene)
Gene: Small nuclear RNA gene on chromosome 2 (130,497,743 to 130,497,849, reverse strand). Ensembl gene ENSG00000251973.
Homologues: Orthologues: macaque U6 (93% identical), macaque U6 (92% identical), guinea pig U6 (77% identical), dog U6 (74% identical), pig U6 (65% identical). Paralogues in human: RNU6-617P (100% identical), RNU6-848P (100% identical), RNU6-1049P (99% identical), RNU6-127P (99% identical), RNU6-1239P (98% identical), RNU6-1268P (98% identical), RNU6-816P (98% identical), RNU6-1021P (93% identical), RNU6-286P (93% identical), RNU6-631P (93% identical), RNU6-749P (93% identical), U6 (93% identical), and 1286 more.